IL1B (interleukin 1 beta)
Diseases named in the same sentence as IL1B in open-access papers (continued):
Sharing a sentence is not in itself a finding about the gene and the disease.
infection (continued). "The classically activated macrophages produce high levels of proinflammatory cytokines such as tumor necrosis factor-α (TNF-α), interleukin-1β (IL-1β), IL-6, and reactive oxygen to protect host against the infection." (PMID 27322250, 2016). "The Tg(il-1b:GFP-F+/+) larvae were also used to visualize the anatomical distribution of Il-1β expression after the infection in the different sites." (PMID 27540375, 2016). "In contrast, after IL-1β treatment or infection with cagA positive strains we observed that β-catenin was translocated to the nucleus." (PMID 27525003, 2016). "The levels of IL-1β induced by a high dose of R. australis were significantly higher than those with the low dose infection at 8 h, 12 h and 16 h p.i.." (PMID 27362650, 2016). "The level of IFNγ was similar after all infections; IL-1β was the highest in PEC after cps1-1 and in spleen after ME49; IL-17A was increased after cps1-1 and ME49 in PEC; IL-10 was increased after RH and ME49 in spleen." (PMID 27721814, 2016). "Compared with the control group, infection with B. melitensis 16M cells led to a change of the inflammatory cytokines IL-1β and IL-18 to varying degrees." (PMID 27907115, 2016). "Card9−/− macrophages secreted 2.5 times more IL-1β than WT BMDMs at both 6 and 24 h post infection, time points known to involve NLRP3 activity in response to Salmonella infection." (PMID 27670879, 2016). "The antigen distribution of TMUV and GPV during infection in geese was coincident with the CD8+ T cell distribution, which was also associated with the high production of IFNγ and proinflammatory cytokine (IL1β and IL6) in virus-preferable tissues." (PMID 27150912, 2016). "IL-8 and CCL3 primarily stimulate chemotaxis of granulocytes, as well as inducing phagocytosis at the site of infection, whereas IL1β is a key mediator of the inflammatory response, being involved in cell differentiation, proliferation and apoptosis." (PMID 27793136, 2016). "In summary, S. aureus induced low but statistically significant increases in mRNA expression of IL-6 in both SM- and OM-HPBCs and a small increase in IL-1β mRNA at 48 h post-infection in OM-HPBCs." (PMID 27446812, 2016). "At 48 and 72 h post infection, mRNA expression of IL-1β, IL-6, IL-8, and TNF-α in mimic-transfected cells was substantially decreased compared to the control mimic." (PMID 27117627, 2016). "The infection induced a very high expression of IL-1β as soon as 1 hpi, and it significantly increased over time, reaching up to 66 times the expression detected in control animals at 5 hpi." (PMID 27540375, 2016). "Intravenously infected piglets showed a peak production of Interleukin 6 (IL-6) and Interleukin 1 beta (IL-1-β) serum concentrations 1 day post-infection (p <0.001) to decrease to normal levels respectively 3 and 5 days post-infection." (PMID 27276874, 2016). "Ierna and colleagues have shown that soluble TNF-α is required for expulsion of T. spiralis in mice, and IL-1β has been suggested to be an important initiator of the inflammatory response during infection." (PMID 27267469, 2016). "Infection of Nod2−/− macrophages induced a small increase in IL-1β production, but suppressed TNF-α production." (PMID 27670879, 2016). "Levels of inflammatory cytokines IL-6 and IL-1β in the CSF at 21 h after infection were higher in rats infected with serotype 6B than 7F, suggesting an association between an exaggerated inflammatory response and worse outcome." (PMID 27009189, 2016). "Since IL-1β has a crucial role in attracting neutrophils to infection sites, our present data suggest that, after recognizing GBS, these phagocytes can amplify their own recruitment through IL-1β production." (PMID 27509078, 2016). "Components of specific pathogens activate different inflammasomes, which once activated in response to pathogen-induced infection, induce the activation of caspases, and the release of mature forms of interleukin-1β (IL-1β) and IL-18." (PMID 27994587, 2016).
infection (continued). "We found higher expression levels of IL1-β and TNFα at different times post-infection in injured larvae compared to injured but uninfected larvae." (PMID 27540375, 2016). "Following infection, IL-1β was significantly attenuated in both serum and PLF from Asc−/− mice compared to the wild type animals." (PMID 27378827, 2016). "Compared with naive animals, the level of IFNγ, IL-1β, IL-17A, and IL-12 was increased at 5 days post infection in PEC." (PMID 27721814, 2016). "Previous studies have demonstrated that production of a mature IL-1β after MVA infection requires a crosstalk between TLR2-MyD88 and NALP3 inflammasome." (PMID 27223301, 2016). "Resident epithelial cells and macrophages at the infection site release cytokines such as interleukin-1β (IL-1β), IL-8, and tumor necrosis factor-α (TNF-α) to induce the expression of P-, E-, and L-selectins on the luminal surface of endothelial cells." (PMID 27467389, 2016). "In our work, differential anatomical distribution of the IL-1β expression was observed between local and systemic infection." (PMID 27540375, 2016). "Our data show increased IL-1β protein expression in Card9−/− BMDMs at 2 and 6 h post infection compared with WT cells." (PMID 27670879, 2016). "The time courses determined for the IL-1β mRNA levels revealed an increase after 6 and 12 h of HGPg infection." (PMID 28083517, 2016). "Pulmonary levels of IFNγ, IL-1α, IL-1β and CXCL1/KC were highly increased in TNFα-deficient mice one month after infection, when severe pathology develops, with a reduction of IL-12/23p40 and p19, in line with transcriptome data." (PMID 27853279, 2016). "Quantitative reverse transcription-PCR data showed that 30 min post PAO1 infection, transcriptions of all tested NF-κB-dependent genes, including IL-1α, IL-1β, IL-6, IFN-γ, MCP-2, MIP1α, TNF-α and TLR2, were significantly increased in Lyn-silenced MH-S cells." (PMID 29263906, 2016). "In this study, largemouth bass injected with a virulent strain of Nocardia seriolae showed a significantly higher expression of IL-1β in the spleen, and kidney at 3 d post-infection." (PMID 27706080, 2016). "Since the cleavage and maturation of IL-1β is mediated by caspase-1 activation, we examined the level of IL-1β 24 h post-infection with the JR32 or the legS2 mutant by ELISA." (PMID 26741365, 2016). "Rickettsia induced significant secretion of IL-1β and IL-18 in vitro by infected mouse bone marrow-derived macrophages (BMMs) as early as 8–12 h post infection (p.i.)in a dose-dependent manner." (PMID 27362650, 2016). "To evaluate the inflammatory response we analysed BAL cell numbers, protein content and IL-1β levels of mice infected with either 108 or 109 CFUs 24 and 48 hours after infection." (PMID 27303806, 2016). "A surprising finding in this study was the decreased level of systemic IL-1β and IL-2 in the SmPCR+ cohort compared to Sm uninf and those with patent infection." (PMID 27152725, 2016). "IL-1β levels were eight fold higher in mice receiving 109 CFUs (148.9 ± 21.5 pg/ml) compared with mice receiving 108 CFUs (18.3 ± 5.6 pg/ml) 24 hours post infection." (PMID 27303806, 2016). "The therapeutic 100 TCID50 group showed transient increase in the expression levels of TNF-α and IL-1β throughout the course of infection and of the IL-12p70 on days 3 and 4 after infection." (PMID 27110056, 2016). "In mouse bone marrow macrophages, the AIM2 inflammasome contributes partially to the production of IL-1β and IL-18 during the infection." (PMID 27994587, 2016). "MEFV has previously been shown to be up-regulated in human monocytes and Mø in response to Burkholderia cenocepacia infection and plays an important role in regulating IL1B release during infection." (PMID 27000047, 2016). "The infection of the transgenic zebrafish line Tg(Il-1b:GFP-F+/+) allowed the visualization of Il-1β gene expression in different organs." (PMID 27540375, 2016).
infection (continued). "NLRP3 activity was instead defective in Il1r1–/– mice, in which the attenuated IL-1β production was concomitant with a reduced disease severity during infections." (PMID 26972847, 2016). "Nlrp3–/– mice showed increased resistance to either infection, as revealed by the reduced fungal or bacterial load, IL-1β production and lung inflammatory cell recruitment." (PMID 26972847, 2016). "The induction of IL-1β mRNA expression and IL-1β protein secretion in medium by HGPg infection was MOI-dependent." (PMID 28083517, 2016). "This is an agreement with our data showing decreased IL-1β production concomitant to reduced CXCL1 release during infection with the ST17 strain." (PMID 27527222, 2016). "Of these, IL-1β is a proinflammatory cytokine which has a crucial role in regulating the defenses of the host during infection." (PMID 27706080, 2016). "Increased IL-1β and activation of NLRP3 inflammasomes were also detected during infection of flaviviruses associated to CNS, including JEV and WNV." (PMID 27610098, 2016). "The release of mature IL-1β is induced in response to infection and it is known to increase host resistance to systemic spread during later stages of the disease." (PMID 27341123, 2016). "IL-1β induction in response to C. albicans was shown previously to depend on the NLRP3 inflammasome in different infection models and NLRP3 was required in the hematopoietic compartment." (PMID 27632536, 2016). "IL-1β is released mainly by macrophages and monocytes as well as by non-immune cells, including endothelial cells and fibroblasts, during cell injury, infection, invasion, and inflammation." (PMID 26797636, 2016). "IL-1β, as a proinflammatory cytokine, mediates the host response to infection through both direct and indirect means." (PMID 27446066, 2016). "Only the lowest dose of OMVs (0.1 μg/mL) that triggered a weak induction of IL-1β transcript allowed a minor additional increase after 48 h of infection." (PMID 27105429, 2016). "The invasion process triggers the production of the pro-inflammatory cytokines IL-8, IL-1β and IL-18 that recruit immune cells to the site of infection leading to inflammation." (PMID 27145267, 2016). "Infection was accompanied by strong mucosal IL-1β staining in bladder tissue sections in C57BL/6 WT mice, Asc-/- and Nlrp3-/- mice after 24 hours." (PMID 27732661, 2016). "In the acute infection model, IL-6 mRNA over-expression by both SM- and OM-HPBCs infected with S. aureus, as well as the weak responses in IL-1β and TNF-α mRNA expressions, were already observed during S. aureus and mesenchymal stem cell interaction." (PMID 27446812, 2016). "Concerning IL-1β, S. aureus induced a significant 1.7-fold increase in mRNA expression in OM-HPBCs after 48 h of infection." (PMID 27446812, 2016). "siRNA knockdown experiments also showed that loss of ASC significantly reduced the induction of caspase-1 activity and IL-1β secretion following infection with M. bovis." (PMID 27043315, 2016). "The immune response triggered by the infection in injured larvae was also assayed by measuring the expression of the proinflammatory genes IL-1β and TNFα." (PMID 27540375, 2016). "Upon infection, they initiate inflammatory responses by releasing cytokines and chemokines, such as IL-1β, IL-18, TNF-α, and CCL3." (PMID 27043315, 2016). "Most of the time, inflammasome-mediated IL-1β production or caspase-mediated pyroptosis is beneficial for the host, as it protects from infection or prevents further damage." (PMID 27672241, 2016). "The M1 macrophages, unlike the M2 macrophages, produce NO and other pro-inflammatory cytokines such as the TNF-α, IL-6 and IL-1β to fight infection." (PMID 26934748, 2016). "After Ft LVS infection IL-1β and IL-18 levels are similar between Aim2- and Nlrp3-deficient mice, yet mice deficient in Aim2, ASC, or caspase-1/11 do not reproduce the survival phenotype of Nlrp3 mice." (PMID 27926940, 2016).
infection (continued). "Intracellular infection with the S. aureus WCH-SK2WT elicited a more consistent innate immune response in comparison to intracellular S. aureus WCH-SK2SCV infection with an increased expression of IL1B, IL6, IL12, MMP9, and TLR2 at 24 h." (PMID 28083514, 2016). "This resulted in an attenuation of the HZ-induced IL-1β maturation and its release identical to infection experiments previously shown." (PMID 26114647, 2015). "It is noted that Tnf and Il1b mRNA expression were sustained at D5 post RSV-LD infection, while Il6 mRNA was only induced acutely at early times of infection, corresponding with the peak of weight loss." (PMID 26336095, 2015). "Cytokines involved in Th17 differentiation, including TGF-β, IL-1β and IL-23, were greatly increased in the mammary gland following S. aureus intramammary infection." (PMID 26230498, 2015). "Since the virulence factor armament of each pathogen is unique, the role of IL-1β and the pathways leading to its activation varies for each infection." (PMID 26500655, 2015). "We also observed that production of TNF-α and IL-1β was reduced in exercising mice, while cathelicidin production was increased, suggesting that suppression of the infection by cathelicidin led to a decrease in cytokine production." (PMID 26542343, 2015). "Thus, our data indicates that Leishmania may employ different GP63-linked strategies to impair secretion and maturation of IL-1β during infection, the downregulation of ROS on the one hand and the cleavage of inflammasome and inflammasome-related proteins on the other hand." (PMID 26114647, 2015). "Since IL-1β is induced via inflammasomes in immune cells, our data strongly suggest that dermatophytes activate keratinocyte inflammasomes during infection." (PMID 25667269, 2015). "Our infection experiments with L. major and L. mexicana revealed an attenuated capability of macrophages to produce and secrete IL-1β when stimulated with the specific and well characterized NLRP3 inflammasome agonist HZ." (PMID 26114647, 2015). "In another study, H37Rv infection in IL-1β knock-out mice showed 10-fold more colony-forming units in lungs at 7 weeks after infection compared with wild type mice." (PMID 25847237, 2015). "Our results demonstrate that Y. pestis activates pro-inflammatory cytokines IL-1β and IL-18 in the lung early during infection." (PMID 25781467, 2015). "After 1 hr of infection followed by 6 hrs of further incubation, we used an ELISA method to measure the IL-1β secretion from cells infected with TOE-A1 to TOE-A6 strains." (PMID 26332984, 2015). "There, we observed that after infection with Leishmania we were able to observe cleavage of pro-IL-1β." (PMID 26114647, 2015). "There was also a significant reduction in the levels of the interleukins IL1-α and IL-1β released when fkh2(6A) was used in the infection model." (PMID 25617770, 2015). "We found less Il1b mRNA in the lungs of Il21r−/− mice than in wild-type (WT) mice after infection with PVM27." (PMID 26269257, 2015). "We found that C. burnetii pre-infection severely inhibited caspase-1 activation and pro-IL-1β processing in response to E. coli." (PMID 26687278, 2015). "On the contrary, the elevated expression of caspase-1 p10, IL-1β and IL-18 by D39 infection was further increased in response to treatment with 3-MA." (PMID 26683708, 2015). "RV14 infection increased the secretion of IL-1β in the supernatants of the untreated cells and the cells pretreated with vehicle at 72 h after infection." (PMID 26462747, 2015). "This inflammasome is a molecular platform that is activated upon cellular infection or stress triggering the maturation of pro-inflammatory cytokines, such as IL-1β and engaging innate immune defences." (PMID 25684031, 2015). "Deletion of IL-1β in blood monocytes blunts the production of IL-22 by ILC3 and increases the susceptibility to infection." (PMID 26269452, 2015).
infection (continued). "And in agreement with previous works, production of mature IL-1β in response to Ft LVS infection is dependent on TLR2 and the inflammasome adaptor ASC." (PMID 25768794, 2015). "Lung-resident myeloid cells represent a potential source of IL-1α and IL-1β at the earliest time point post-infection." (PMID 25621893, 2015). "Exogenous IL-1β was found to be protective only when administered during the first six days post infection." (PMID 25768794, 2015). "The inflammatory markers IL-6, IL-1α and IL1-β were expressed at similar levels in both infections at early times, while TNFα was preferentially present in S. mitis infections." (PMID 26171605, 2015). "In agreement, the infected mice also showed significant accumulation of serum IL-1β during the infection." (PMID 26367131, 2015). "Treatment with anti-diabetic drugs metformin and glibenclamide also reduced IL-1α and IL-1β secretion in infection and cytokine-primed adipose tissue." (PMID 25849717, 2015). "In contrast, purified Vero-derived DENV-2 16681 exhibited antibody-enhancement of both infection and IL-1β induction." (PMID 26301593, 2015). "The expression of mRNA encoding several interleukins was also induced in the infected mouse uterus at 28 days post-infection, including Il1b, Il12a, Il12b, Il16, Il18, and Il27." (PMID 26779389, 2015). "Serum total superoxide dismutase (SOD) activity, malondialdehyde (MDA) level, tumor necrosis factor alpha (TNF-α), C-reactive protein (CRP) and interleukin-1 beta (IL-1β) levels were measured at 5, 10, 15, 20 days post infection (dpi)." (PMID 25723390, 2015). "In the present work we addressed how Leishmania parasites can attenuate IL-1β production through the leishmanial virulence factor GP63 during infection." (PMID 26114647, 2015). "This study also confirmed that there is a time lag of 6 to 8 hours until APR becomes positive after infection onset as APR is a protein produced in the liver in response to stimulation with IL-1β and IL-6." (PMID 25667565, 2015). "This serpin can prevent the proteolytic activation of interleukin-1β, then block the cleavage of pro-IL-1β by ICE thereby suppressing an interleukin-1β response to infection and decreasing the secretion of IL-1β." (PMID 25888442, 2015). "IL-1β can also provide protection against infections by activating several host responses including neutrophil recruitment and stimulating the Th17 response." (PMID 25879288, 2015). "This conclusion was also supported by the observation that Il-1r1-/- or Il-1b-/- mice appear to be able to control the infection, at least in its early stages, but eventually succumbed." (PMID 25768794, 2015). "In the WT mice there was a trend towards greater BALF levels of TNF-α, KC and IL-1β with the smooth compared to the rough infection, whereas in the CF mice this trend was reversed." (PMID 25675351, 2015). "Collectively, these results provide convincing evidence that Leishmania GP63 is the causative factor for an impaired IL-1β production by the NLRP3 inflammasome complex, which was observed after infections with Leishmania parasites prior to cell stimulation." (PMID 26114647, 2015). "IL-1β, a critical cytokine in the orchestration of the complex immune response to infection and injury, was originally described as a peripheral immune cell mediator." (PMID 25807081, 2015). "We also investigated the role of S. pneumoniae D39-induced ROS on the production of IL-1β at the late phase (8 h) of infection." (PMID 26683708, 2015). "Instead, DENV-2 16681 propagated in mosquito cells displayed ADE of both infection and IL-1β secretion." (PMID 26301593, 2015). "First, both the strains induced high levels of IL-1β, and, second, the relative difference in IL-1β production changed with time during infection." (PMID 26047469, 2015). "As previous studies suggested a dysregulation of IL-1β levels after infection with Leishmania parasites, we herein investigated the underlying mechanisms." (PMID 26114647, 2015).